BARD1 (BRCA1 associated RING domain 1)
Diseases named in the same sentence as BARD1 in open-access papers (continued):
Sharing a sentence is not in itself a finding about the gene and the disease.
tumor (continued). "When testing the extent of DNA damage, mammary gland tissues transplanted with cells expressing WT or single-mutant BARD1 had no detectable DNA lesions in, whereas tumor masses with cells bearing BARD1P24S/R378S had many DNA breaks marked by γH2AX." (PMID 33623049, 2021). "In our cohort, we identified five tumours without BARD1 (both β and FL) expression, to assess BARD1 gene status we performed FISH analysis." (PMID 33530592, 2021). "All analyzed pilot group RMS tumour tissue expressed BARD1 FL and BARD1 β (n = 7/7; 100%), while in adjacent tissue, one did not express BARD1 FL, and two did not express BARD1 β (n = 5/7; 71%)." (PMID 33530592, 2021). "We found higher expression of beta isoform in tumour compared to healthy tissue with no such changes concerning BARD1 full-length." (PMID 33530592, 2021). "Bard1+/− heterozygous mice were indistinguishable from their wild-type littermates in terms of viability and fertility and did not develop detectable tumours by 21 months of age." (PMID 32726901, 2020). "Full-length Bard1 proteins act as tumor suppressor with or without interaction with Brca1 whereas different splice variants detected in various cancers have oncogenic properties." (PMID 30760980, 2019). "Although the precise role(s) of BRCA1/BARD1 in tumor suppression have not been fully established, ample evidence indicates that this heterodimer is required to maintain genomic stability following DNA damage (see reviews)." (PMID 21103343, 2010). "Until recently, the role of the BRCA1/BARD1 heterodimer in tumour suppression had not been evaluated." (PMID 19904273, 2009). "Together, these findings suggest that the absence of BARD1 promoter methylation, and the consequent maintenance of BARD1 expression, may play a tumor-suppressive role in certain cancer contexts." (PMID 41009605, 2025). "The overlap with differentially expressed genes in tumor versus normal breast tissues identified a subset of 24 genes, 4 of which associated to the highest negative prognostic impact in BC (KHDRBS1, EXO1, CHEK1, BARD1)." (PMID 35217791, 2022). "Our study thus uncovers a previously unanticipated buffering relationship between CtIP and BARD1 to ensure faithful DNA replication and maintain genome stability and corroborate the significance of the genetic interaction between CtIP and the BRCA1-BARD1 complex for tumor suppression." (PMID 35203293, 2022). "Intriguingly, the expression of BARD1 isoforms did not correlate with tumor grade or stage." (PMID 32708251, 2020). "Additionally, we demonstrated a role for FL BARD1 as tumor suppressor that is independent of DNA damage response that needs major elucidation in the next future." (PMID 32047556, 2020). "Indeed, whereas FL BARD1 protein acts as tumor-suppressor with and without BRCA1 interactions, aberrant splice variants of BARD1 have been detected in various cancers and have been shown to play an oncogenic role." (PMID 29292755, 2017). "The oncogenic potential of truncated BARD1 isoforms might be related to their lack of some important domains, in particular the RING N-terminal domain, consistent with the loss of BARD1 tumor-suppressor functions." (PMID 24349422, 2013). "Indeed, in the early response to UV and MMS, but not to IR, dispersion of BRCA1/BARD1 from nuclear foci is accompanied by ubiquitin-mediated degradation of both tumor suppressors." (PMID 21103343, 2010). "In contrast, the addition of BRCA1-related parameters (mRNA, protein and BARD1 ligated to BRCA1) to the same three conventional prognostic factors (node invasion, tumor size and CK5/6 expression) did not improve the model performances." (PMID 26490435, 2015).
tumor (continued). "In the present study, we have not investigated if that tumor suppressor role for FL BARD1 is dependent from BRCA1, but we should consider that FL BARD1 might act in additional pathways involved in carcinogenesis through additional binding partners that remain not investigated." (PMID 32047556, 2020).
cancer (156 papers, 2006 to 2026). A tumor composed of atypical neoplastic, often pleomorphic cells that invade other tissues. "Several germline variants in BARD1, associated with elevated risk for breast, ovarian, pancreatic, and other cancers, are mappable to highly conserved domains." (PMID 41009605, 2025). "Ultimately, we have generated strong functional evidence for the pathogenicity and benignity for 4,569 missense variants and show that LoF BARD1 variants increase cancer risk." (PMID 41282735, 2025). "This enrichment provides orthogonal evidence that SGE in haploid cells measures phenotypes relevant to BARD1-associated cancer predisposition." (PMID 41282735, 2025). "This study aimed to investigate the frequency and distribution of the BARD1 variant c.1518_1519delinsCA (p.Val507Met) in a cohort of 920 patients undergoing genetic testing for hereditary cancer predisposition." (PMID 41301857, 2025). "BARD1 mutations can vary across different ethnic groups, which is important for assessing cancer risk and developing effective monitoring strategies." (PMID 40805222, 2025). "A role for regulation of DNA repair mechanisms through binding to BRCA1-associated RING domain 1 (BARD1) was also described in several cancer types." (PMID 40427133, 2025). "Ultimately, our results demonstrate that the variant effect measurements generated by SGE are relevant to disease and that LoF missense variants across all three BARD1 functional domains are associated with increased cancer risk." (PMID 41282735, 2025). "Specific BARD1 isoforms are linked to cancer; for example, BARD1β is associated with neuroblastoma susceptibility, while BARD1δ, an isoform with a deletion, is linked to tumor progression and genomic instability." (PMID 38539439, 2024). "BARD1 mutations have been identified in prostate and ovarian cancer without significantly affecting the risk of developing either cancer." (PMID 39233942, 2024). "BARD1 is a gene that encodes a protein that plays a critical role in the development and progression of different types of cancer." (PMID 37727789, 2023). "Meanwhile, the proportion of BARD1+ malignant cells was significantly positively correlated with cancer-associated fibroblasts (CAF)." (PMID 37727789, 2023). "BARD1 was identified as a BRCA1 interacting protein and mutations in BARD1 also lead to an increased incidence of cancer." (PMID 36716349, 2023). "This means that mutations in BARD1 can be used as a diagnostic tool to identify individuals at higher risk of developing certain types of cancer." (PMID 37727789, 2023). "In recent decades, researchers have studied the role of the BARD1 (BRCA1-associated RING domain 1) gene in cancer progression and its usage as a prognostic biomarker for cancer and a potential candidate for targeted cancer therapy." (PMID 35650591, 2022). "Together, these findings from accumulating evidence have concluded a high/moderate risk of breast (or others) cancers harnessed to various BARD1 polymorphisms in a context dependant manner." (PMID 35650591, 2022). "Multiple splice variants or functional isoforms of BARD1 comprising of variable exon composition are expressed in human and murine cancers." (PMID 35406624, 2022). "Studies have indicated that cancer cells overexpressing BARD1 are resistant to DNA-damaging chemotherapy and radiotherapy, thus BARD1 overexpression is associated with poor prognosis in cancer patients." (PMID 34789768, 2021). "Regarding population data, BARD1 c.1977A>G variant is present in approximately 1 in 170 individuals with European ancestry, being more common than most cancer-predisposing variants." (PMID 34824355, 2021). "Several scientific evidence shows that cancer-associated BARD1 isoforms act as a driving force for carcinogenesis." (PMID 33530592, 2021). "We have recently published a case–control study investigating the role of BARD1 in cancer predisposition in a Spanish HBOC cohort of 4015 individuals." (PMID 34824355, 2021).
cancer (continued). "In 2017, a positive statistical association of BARD1 variants with BC was reported in a large sample size of approximately 30,000 BC cases and 30,000 cancer-free controls." (PMID 32726901, 2020). "Given that risk for cancer in carriers of BARD1 variants is equivocal, we questioned if there are recommendations should potentially pathogenic variants be identified by panel testing." (PMID 32726901, 2020). "BARD1 is also important for genome stability and several cancer-associated BARD1 missense mutations localize to its BRCT domains." (PMID 33024116, 2020). "The design of future studies to assess the risk of BARD1 pathogenic variants in different cancers will be crucial to determine if translation to patient care in the clinic is appropriate." (PMID 32726901, 2020). "Regardless, the observation that a BARD1 variant was found in an individual with three primary cancers suggests a strong possibility that it is associated with risk to cancer." (PMID 32726901, 2020). "There are many other single nucleotide variants of BARD1 that are significantly associated with NB susceptibility, however, the details regarding their role in cancer prognosis still need to be further investigated." (PMID 32708251, 2020). "On the other hand, high-risk variants that fall into introns correlate with high expression of cancer-associated BARD1β isoform that antagonizes FL BARD1 functions and acts as a driving force for carcinogenesis." (PMID 32047556, 2020). "Although potentially pathogenic BARD1 variants have been reported, the role of BARD1 in cancer predisposition remains inconsistent." (PMID 32726901, 2020). "The prevalence of potentially pathogenic germline BARD1 variants has been investigated in colorectal, endometrial and pancreatic cancers." (PMID 32726901, 2020). "Subsequent studies reported consistent positive results and proposed BARD1 as a candidate cancer predisposing gene where variants confer low–moderate risk for BC, especially for triple-negative BC (TNBC)." (PMID 32726901, 2020). "In studies of ≥500 cancer cases, the prevalence of potentially pathogenic BARD1 variants ranged from 0.18–0.53%, 0.67–0.9%, and 0.07–0.23% in BC, TNBC and OC cases, respectively." (PMID 32726901, 2020). "Several cancer-associated BRCA1 RING domain variants abolish binding to BARD1 and the E3 ubiquitin ligase activity." (PMID 32722046, 2020). "BARD1 variants were also commonly found in cancers of the ovaries, prostate, brain, lung, and gastrointestinal tract." (PMID 32708251, 2020). "According to the most recent TCGA database (as of July 2020), 169 BARD1 mutations have been identified in a variety of cancers, including those discussed here." (PMID 32708251, 2020). "In BARD1 targeted sequencing studies that investigated ≥500 cancer cases, the allele frequencies ranged between 0.02%–49% and 0.03%–48% in BC and OC cases, respectively." (PMID 32726901, 2020). "Estimates of the lifetime risk for cancer that are associated with carriers of a potentially pathogenic BARD1 variant have been reported for BC and OC in case-control studies, although most involved familial BC cases." (PMID 32726901, 2020). "A number of studies estimated the cancer risk associated with specific variants in BARD1 in BC and hereditary BC and/or OC syndrome families." (PMID 32726901, 2020). "Here, we aim to review what is known about BARD1 as a candidate cancer predisposing gene and discuss challenges facing researchers aiming to discover additional cancer predisposing genes." (PMID 32726901, 2020). "It is worth mentioning that several of the BARD1 missense variants have been shown to cosegregate in families with cancer." (PMID 32679805, 2020). "More functional studies need to be conducted to determine the pathogenicity of different BARD1 variants in various cancer types." (PMID 32708251, 2020).
cancer (continued). "The first statistical association was reported by analyzing the BARD1 c.1670G>C; p.Cys557Ser variant in cancer cases from Finnish, Nordic, and Icelandic populations versus population-matched cancer-free controls." (PMID 32726901, 2020). "Initial screening revealed pathogenic variants in known cancer genes, including BARD1:p.Trp91* detected in a cancer-free individual, and MEN1:p.Glu260Lys detected in a BC patient." (PMID 31681433, 2019). "In this paper, potentially pathogenic BARD1 variants were identified in a dataset of 10,389 cancer samples from 33 different cancers." (PMID 30925164, 2019). "The HDR results also reveal a correlation between BARD1 variants that cause a loss of DNA repair function with those that are likely cancer predisposing." (PMID 30925164, 2019). "The ablation of BARD1 in mice leads to cancer susceptibility, and probable disease-causing mutations are found in patients with breast cancer." (PMID 30874560, 2019). "In this paper, whole exome sequencing of over 10,000 cancer samples from 33 cancer types identified from somatic mutations and loss of heterozygosity in tumors 76 potentially cancer-associated BARD1 missense and truncation variants." (PMID 30925164, 2019). "More recently, several studies reporting results for targeted sequencing with cancer-predisposition gene panels, including BARD1, have been published." (PMID 31142030, 2019). "In this large case-control study, we provided strong evidence that BARD1 is a low/moderate cancer susceptibility gene." (PMID 31142030, 2019). "A private stop-gain variant was detected in the third of eleven exons of BARD1 (c.273G > A) in a cancer-free mother (> 60 years old) of a HBOC patient (diagnosed at 37 years of age)." (PMID 31681433, 2019). "This variant was shown to abolish the interaction of BRCA1 with the partner protein BARD1, in a manner similar to the known cancer predisposing variant p.Cys61Gly." (PMID 30696104, 2019). "In this study, we found: 1) from 10,389 cancer samples across 33 cancer types, 76 BARD1 missense variants were identified as potentially pathogenic and were selected for functional analysis." (PMID 30925164, 2019). "BARD1 missense variants with potential cancer predisposition were identified in a set of 10,389 TCGA cancer samples from 33 cancer types using whole exome sequencing." (PMID 30925164, 2019). "In this paper, we identified 76 potentially cancer-associated BARD1 variants from analysis of over 10,000 tissue samples from people with cancer." (PMID 30925164, 2019). "Genetic analysis revealed a pathogenic variant in BARD1, which is associated with an increased risk of developing certain types of cancer." (PMID 28174632, 2017). "Contrary deleterious BARD1 mutations are infrequent in cancer because the cells lose both DNA repair capabilities and pro-apoptotic function." (PMID 29292755, 2017). "We confirm that even if pathogenic somatic mutations are relatively infrequent, BARD1 can be considered a cancer driver gene (CHASM gene score = 0.73; CHASM gene p-value = 0.0000004)." (PMID 29292755, 2017). "Further complete gene sequencing or whole genome sequencing projects are warranted to investigate the contribution of rare non-coding variants of BARD1 in conferring cancer risk." (PMID 29292755, 2017). "The breast cancer-associated protein, BARD1 (BRCA1-associated RING domain protein), co-localizes with BRCA1 in nuclear foci." (PMID 26402707, 2015). "We will continue to review internal cosegregation, phenotype, and frequency data on BARD1 mutations and variants in our cohort to aid in clarifying the contribution of this gene to hereditary cancer susceptibility." (PMID 24763289, 2014). "BRCA1 nuclear transport and ubiquitin E3 ligase enzymatic activity are tightly regulated by the BRCA1 dimeric binding partner BARD1 and further modulated by cancer mutations and diverse signaling pathways." (PMID 24278741, 2012).
cancer (continued). "These variants may confer low to moderate penetrance effects, which still require more evidence and convincing risk assessments for recommendations on surveillance for carriers of BARD1 pathogenic variants concerning other cancers." (PMID 40805222, 2025). "Accordingly, BARD1 is included on genetic testing panels for cancer risk." (PMID 41282735, 2025). "Thus, our study immediately increased the utility of clinical genetic testing targeting BARD1—both in its ability to inform patients on their cancer risk and to guide treatment for cancer patients." (PMID 41282735, 2025). "Thus, our inability to understand how missense variation affects BARD1 function, and classify variants accordingly, limits cancer risk assessment and treatment guidance for many individuals." (PMID 41282735, 2025). "Biallelic loss of HRR genes, especially BRCA1, BRCA2, RAD51D, RAD51 C, and PPP2R2 A was linked to higher HRD scores in BRCA-associated cancers, while BARD1, RAD51D, RAD54L, BRCA1, and MRE11 were associated with elevated HRD scores in in other cancer types (non-BRCA cancers)." (PMID 40420266, 2025). "Additionally, the role of pathogenic variation of the BARD1 gene in the development and prognosis of breast and other cancers is an ongoing debate requiring further studies to determine the mutation’s clinical significance." (PMID 39233942, 2024). "Alternatively, treating these patients with other chemo therapeutic agents such as HU, for which BRCA1/BARD1 E3-deficient cells are still sensitive might open a therapeutic opportunity for cancer treatment." (PMID 38769345, 2024). "Off-target information with potentially serious clinical implications that was previously unknown to the family was provided only to one family, with the finding of an inherited variant in BARD1 indicating a highly increased cancer risk." (PMID 38256266, 2024). "BARD1 is now included in the clinical genome for cancer susceptibility testing." (PMID 37727789, 2023). "Mutation of BARD1 was implicated in multiple types of cancer." (PMID 36430822, 2022). "Also, a whole-exome sequencing study on 10,000 cancer samples from 33 cancer types has successfully identified 76 BARD1 cancer-associated missense and truncation variants." (PMID 35650591, 2022). "In addition, it was reported that BARD1 isoforms expression is significantly associated with a decrease in the survival rate of cancer patients." (PMID 35650591, 2022). "To date, the role of BARD1 in cancer predisposition remains inconclusive." (PMID 33498765, 2021). "To date, little is known about cancer susceptibility in carriers of BARD1 mutations." (PMID 34771627, 2021). "Furthermore, 354 individuals from gnomAD non-cancer database harbored BARD1 c.1977A>G variant (carrier frequency = 0.6%), one of them in homozygosis." (PMID 34824355, 2021). "Many cancer-associated BARD1 mutations localize to its BRCT domains." (PMID 33024116, 2020). "This suggests that the effect size of BARD1 c.1670G>C; p.Cys557Ser could be small, that is, it could confer a low–moderate risk to cancer relative to the high risk associated with BRCA1/BRCA2 pathogenic variants." (PMID 32726901, 2020). "The presence of BARD1 variants in other cancer types suggests that they may also play a role in risk in these diseases." (PMID 32726901, 2020). "The contribution of BARD1 variants to cancer risk or disease progression in carriers of pathogenic variants in known cancer predisposing genes is unknown." (PMID 32726901, 2020). "The aberrant expression of BARD1 is associated with the drivers of various types of cancer." (PMID 31623294, 2019). "BARD1 is a potentially predisposing BC gene, however, the rarity of its mutations and an insufficient family/study size have hampered corroboration and estimation of the associated cancer risks." (PMID 31142030, 2019).